APLN (apelin)
Diseases named in the same sentence as APLN in open-access papers (continued):
Sharing a sentence is not in itself a finding about the gene and the disease.
preeclampsia (continued). "Exercise increases apelin levels to reduce preeclampsia symptoms by increasing eNOS, NO, placental growth factor (PlGF), and VEGF and decreasing levels of fms-like tyrosine kinase 1 (sFlt-1), soluble endoglin (sEng), and oxidative stress." (PMID 37964253, 2023). "Apelin mRNA and protein levels are reduced in women with preeclampsia, and treatment with apelin improves the symptoms of preeclampsia symptoms, stimulates eNOS/NO signaling, and reduces oxidative stress levels." (PMID 37964253, 2023). "Exercise can prevent gestational diabetes and preeclampsia by modulating levels of placentokines and exerkines, such as apelin, adiponectin, leptin, irisin, and chemerin." (PMID 37964253, 2023). "Studies showed that apelin significantly ameliorates preeclampsia symptoms, impaired endothelial nitric oxide synthase/nitric oxide signaling, and reduces oxidative stress activation in mice." (PMID 36093083, 2022). "There is evidence that after the occurrence of preeclampsia, the level of maternal apelin to dilate blood vessels to cope with maternal hypertension increases." (PMID 36093083, 2022). "Studies have shown that decreasing levels of apelin, endothelial nitric oxide synthase (eNOS), and nitric oxide (NO) contribute to the pathogenesis of preeclampsia." (PMID 36093083, 2022). "Although several studies demonstrated a downregulated apelin/APJ system in preeclampsia, others found increased apelin maternal levels and placenta expression in preeclampsia compared to healthy women." (PMID 34819954, 2021). "In accordance with these results, apelin administration has been showed reduction in blood pressure and proteinuria in the preeclampsia models that are created by lowered uterine perfusion pressure." (PMID 33850656, 2021). "In another study, these results were questioned, and a reduction in apelin values was demonstrated in pregnant women with preeclampsia." (PMID 34577885, 2021). "Observations made by our team confirm that fetal DNA is more common in pregnant women with preeclampsia who have a higher concentration of apelin." (PMID 34577885, 2021). "It has been established that serum apelin levels were significantly decreased among patients with preeclampsia." (PMID 33321877, 2020). "Based on the animal models (e.g., apelin and its receptors in the rodent preeclampsia models), future implementation of adipokines and their receptors as new therapeutic targets appears promising but requires further validation in humans." (PMID 33321877, 2020). "Future studies are needed to investigate the tissue-specific mechanisms of apelin’s actions in preeclampsia." (PMID 31189936, 2019). "Further studies are warranted on investigating the mechanisms of apelin actions in the kidney in preeclampsia." (PMID 31189936, 2019). "This study demonstrates improved hemodynamic responses and renal injury without fetal toxicity following apelin administration suggesting a role for apelin in the regulation of maternal outcomes in preeclampsia." (PMID 31189936, 2019). "In short, the levels and the distribution patterns of apelin and its receptor in human placenta suggest a potential of this peptide for therapeutic targeting in preeclampsia." (PMID 31189936, 2019). "In contrast to adiponectin and leptin, studies about the regulation of chemerin, visfatin, resistin and apelin in gestational diabetes, preeclampsia and intrauterine growth restriction are limited." (PMID 31505789, 2019). "Our study opens the possibility of considering apelin as an important mediator of hemodynamic and renal pathophysiology in preeclampsia due to its blood pressure-lowering and reno-protective effects." (PMID 31189936, 2019). "During human gestation APLN is involved in pregnancy by (i) regulation of blood pressure and angiogenesis in the preeclampsia pathophysiology; (ii) effects on plasma volume expansion in foetal growth; and (iii) regulation of glucose metabolism in the gestational diabetes pathophysiology." (PMID 40392420, 2025).
preeclampsia (continued). "Apelin’s ability to exert pleiotropic effects on the inhibition of inflammation, angiogenesis, vasodilation, and oxidative stress have been successfully exploited in the treatment of preeclampsia." (PMID 39457235, 2024). "Furthermore, apelin improves the disrupted eNOS/NO signaling pathway and inhibits the activation of oxidative stress, and hence, ameliorates the symptoms of preeclampsia." (PMID 39457235, 2024). "Exercise and apelin seem to prevent preeclampsia through these processes." (PMID 36093083, 2022). "As higher apelin concentrations are expected in the last trimester of normal pregnancy, lower maternal concentrations may play a key role in the etiology of preeclampsia that is primarily characterized by pathological angiogenesis." (PMID 34819954, 2021). "When the angiogenic and vasodilatation effects of apelin are considered, increasing apelin circulating levels in preeclampsia patients may affect mother and fetus outcomes positively by improving the maternal adaptation to pregnancy." (PMID 34819954, 2021). "Restoring angiogenic/antiangiogenic balance, improving antioxidant status, and inhibiting inflammation may be engaged in the beneficial effects of apelin in preeclampsia." (PMID 34819954, 2021). "Our study found higher concentrations of apelin in patients with preeclampsia." (PMID 34577885, 2021). "In conclusion, our study demonstrated that apelin ameliorated the pathogenesis of preeclampsia." (PMID 34819954, 2021). "Therefore, we designed this project to explore the possible implications of apelin-13 on kidney functions in L-NAME induced rat model of preeclampsia and to distinguish the potential involved processes." (PMID 33850656, 2021). "Apelin is currently used to treat preeclampsia on animal models." (PMID 34577885, 2021). "Apelin is a potential therapy for prevention and treatment of preeclampsia." (PMID 34819954, 2021). "Moreover, alternations in apelin levels were also identified between the groups of patients diagnosed with mild and severe preeclampsia." (PMID 33321877, 2020). "Overall, apelin improved renal pathology in addition to lowering oxidative stress markers, suggesting that (Pyr1)-apelin-13 may provide reno-protection in preeclampsia." (PMID 31189936, 2019). "Since heart weight was greater in TGA-PE rats, we explored whether preeclampsia altered systolic function and whether (Pyr1)-apelin-13 had affected ejection fraction, stroke volume, cardiac output, or relative posterior wall thickness." (PMID 31189936, 2019). "Our findings suggest that (Pyr1)-apelin-13 may be beneficial for the treatment of preeclampsia due to its hemodynamic and reno-protective effects." (PMID 31189936, 2019). "Moreover, preeclampsia-related oxidative stress-induced placental dysfunction is related to decreased placental APLN expression, and elevated circulating APLN may be a somewhat effective marker to distinguish pre-eclamptic subjects from healthy pregnant women." (PMID 40392420, 2025). "Thus, an effective treatment to prevent and treat preeclampsia is required, and apelin might be a novel potential agent that helps in diagnosis and treatment of preeclampsia." (PMID 34819954, 2021). "It seems that the reduced apelin concentration in the placenta may affect the migration of trophoblast cells along the spiral arteries and interfere with the proper vascularization, not only in preeclampsia but also in FGR." (PMID 34577885, 2021). "Interestingly, plasma and/or tissue expression of chemerin, resistin, visfatin and apelin might be associated with various female reproductive disorders including PCOS syndrome, gestational diabetes, preeclampsia, and uterine growth restriction." (PMID 31505789, 2019). "In preeclampsia, oxidative markers such as malondialdehyde (MDA) increase significantly, and levels of NO, apelin, and eNOS decrease significantly." (PMID 36093083, 2022).
preeclampsia (continued). "Inefficient Apelin and APJ appear to help initiate preeclampsia by reducing angiogenic activity in the placenta." (PMID 36093083, 2022). "Recent studies have also identified decreased apelin and APJ as important factors in preeclampsia at the placentas." (PMID 36093083, 2022). "So far, the participation of the apelin/APJ system has been studied in the regulation of placenta function, foetal growth, but also in the context of the development and prevention of pregnancy pathologies such as gestational diabetes, preeclampsia or IUGR." (PMID 33803239, 2021). "Apelin and exercise increase AMPK, PGC-1α, PI3k, and AKT1 leading, to stimulation of GLUT4 and GLUT1 in pregnant rats while also stimulating eNOS/NO, increasing PlGF, decreasing sFlt-1, decreasing sEng, and reducing oxidative stress to improve preeclampsia symptoms." (PMID 37964253, 2023). "As apelin has been involved in blood pressure regulation, angiogenesis, and fluid balance, apelin and its receptor (APJ) might play a significant role in the pathophysiology of preeclampsia." (PMID 34819954, 2021).
gastric cancer (16 papers, 2014 to 2025). A primary or metastatic malignant neoplasm involving the stomach. "This review synthesizes evidence demonstrating how circRNAs modulate Notch activity through miRNA sponging (e.g., circ‐NOTCH 1 promoting gastric cancer metastasis via miR‐637/apelin axis), protein interactions, and peptide encoding." (PMID 40761890, 2025). "In gastric cancer (GC) tissue, the apelin level was closely associated with clinical features and prognosis in GC patients." (PMID 29875677, 2018). "Nevertheless, tumour-associated apelin, instead of serum apelin levels, is closely connected with more advanced clinical features, including tumour differentiation and distant metastases in the case of gastric cancer." (PMID 30127323, 2018). "In addition, the study reported that high apelin expression was closely associated with high invasion and metastatic phenotype of gastric cancer: they also conducted that high expression of apelin was correlated with poor prognosis and shorter overall survival in gastric patients." (PMID 30984306, 2019). "APLN also stimulates cell migration in oral squamous cell carcinoma 29, human lung adenocarcinoma 30, and gastric cancer." (PMID 36632453, 2023). "In gastric cancer, the overall survival of patients with high expression of APLN in tumor was shorter than those with low expression." (PMID 36614283, 2023). "Moreover, this study found several prognostic markers worth exploring: APLNR is a risk factor for GC, so blocking the Apelin/APLNR axis to inhibit the development of gastric cancer is a promising new therapy." (PMID 35174205, 2022). "High APLN level in tumor tissue predicted worse outcome for patients with gastric cancer and muscle-invasive bladder cancer." (PMID 36193059, 2022). "It has been reported that apelin overexpression was related to poor prognosis in lung cancer, oral cancer, prostate cancer, and gastric cancer." (PMID 30984306, 2019). "Apelin also increased the migratory abilities of human lung adenocarcinoma, gastric cancer and oral squamous cell carcinoma." (PMID 29875677, 2018). "Some data indicated that apelin stimulated the migration of several types of cancer cells, like human lung adenocarcinoma, gastric cancer and oral squamous cell carcinoma." (PMID 30127323, 2018). "However, the association of Apelin and gastric cancer remain largely unknown." (PMID 27733135, 2016). "Correlation of apelin with hsCRP can reflect a presumable role of apelin in systemic inflammatory response in esophageal and gastric cancer." (PMID 25049439, 2014). "Additionally, this miRNA targets apelin, another gene that is highly expressed in gastric cancer cells and tissues." (PMID 40761890, 2025). "APLN facilitates the migration of oral squamous cell carcinoma cells and gastric cancer cells." (PMID 36632453, 2023). "APLN promotes the migration of gastric cancer cells 31, while in lung adenocarcinoma, apelin-13 (a 13-amino acid oligopeptide that serves as the ligand for the APLN receptor) enhances cancer cell migration via phosphorylation of the PAK1-cofilin signaling pathway." (PMID 36632453, 2023). "Previous studies showed that apelin could induce the expression of matrix metalloproteases in gastric cancer cells." (PMID 30127323, 2018). "Moreover, apelin peptides increased migration and invasion abilities of several types of cancer, including lung adenocarcinoma and gastric cancer." (PMID 30127323, 2018). "Clinical trials using apelin and apelin inhibitors have not been reported on PubMed to date, but apelin receptor expression has been reported to correlate with prognosis in patients with gastric cancer who were treated with chemoradiotherapy." (PMID 38238841, 2024). "In gastric cancer, tumor apelin levels were elevated, but, interestingly, this was not reflected by higher circulating apelin levels." (PMID 33707612, 2021).
gastric cancer (continued). "Moreover, apelin can affect the invasion of breast cancer cells by inducing the expression of MMP-1, and in the case of gastric cancer cells, MMP-1 and MMP-9 levels were elevated." (PMID 30127323, 2018).
colon carcinoma (15 papers, 2015 to 2025). "Proteomic analysis reveals reciprocal regulation between apelin and apelin-dm on proteins associated with clinical outcomes in colon cancer patients." (PMID 39962271, 2025). "Apelin, an endogenous peptide implicated in the progression of multiple cancers, including lung, hepatocellular, and colon cancer, facilitates TIMP-2-dependent PCa cell migration and invasion." (PMID 38790213, 2024). "Collectively, these results indicate that APLN-DM induces the expression of proteins associated with a favorable clinical outcome and limits the expression of proteins induced by APLN that are involved in the poor prognosis of colon cancer." (PMID 39962271, 2025). "Overall, apelin downregulation in muscles seems a hallmark of cancer cachexia regardless of the species (Rattus Norvegicus, Mus musculus, Homo sapiens) or the tumor type (hepatoma, sarcoma, lung or colon carcinomas)." (PMID 35406586, 2022). "Given the co-expression of apelin, apelin receptor and Furin, that we identified in colon tissues, colon carcinoma cells, and endothelial cells, we sought to evaluate their expression and colocalization in both normal and colon cancer tissues." (PMID 39962271, 2025). "Taken together, these findings indicate that the increased co-expression levels of apelin, the apelin receptor, and/or Furin are associated with CRC tumors, suggesting a potential role for these proteins in colon cancer progression and metastasis." (PMID 39962271, 2025). "To identify the pathways mediated by apelin-dm involved in the repression of the malignant phenotype of colon cancer cells, we performed proteome analysis of cancer cells and the same cells expressing APLN and APLN-DM." (PMID 39962271, 2025). "Apelin-dm exhibited also a pronounced inhibitory effect on colony formation and migration of colon cancer cells, endothelial cells, and smooth muscle cells." (PMID 39962271, 2025). "We next explored the correlation between the expression of APLN and APLNR with genes that are dysregulated by APLN or APLN-DM expression in cancer cells, and involved in prognosis of colon cancer patients." (PMID 39962271, 2025). "We report apelin-specific cleavage and activation by Furin as a key player in colon cancer and early events of colon cancer and liver cells interaction leading to metastasis." (PMID 39962271, 2025). "When expressed in colon cancer cells or administered pharmacologically to mice with colon cancer tumors, apelin-dm represses the malignant and metastatic phenotype of cancer cells." (PMID 39962271, 2025). "In our study, we observed the co-expression of apelin and its receptor in both primary and metastatic tissues of colon cancer patients." (PMID 39962271, 2025). "In soft-agar assays, apelin-dm significantly inhibited the clonogenicity of colon cancer cells, countering the apelin-induced increase in colony formation." (PMID 39962271, 2025). "In the case of colon cancer, apelin and APJ expression is elevated in tissues of colon adenocarcinoma and the human colon carcinoma cell line LS180." (PMID 36776217, 2023). "Regarding combination therapies assessed in in-vivo, overexpressed APLN was reported to promote the maturation of the cancer vasculature and subsequently enhanced its immune therapy efficiency in orthotopic colon cancer models." (PMID 35079698, 2021). "Apelin peptides treatment increased the ratio of filamentous (F-actin) to monomeric (G-actin) actin in all cytoplasmic fractions of colon cancer cells used." (PMID 30127323, 2018). "Exogenous apelin had anti-apoptotic effects on colon cancer cells, whereas in human colon cancer cell lines, this peptide stimulated proliferation through the JAG-1/Notch3 signalling pathway." (PMID 30127323, 2018). "In colon cancer cells apelin peptides increased F:G actin ratio, which suggests that apelin shifted the actin balance onto actin polymerisation in tested cells." (PMID 30127323, 2018).